DOCK2 (dedicator of cytokinesis 2)
Description:
Guanine nucleotide exchange factor (GEF) that activates monomeric GTPases by catalysing the release of bound GDP in exchange for free GTP. Activates RAC1 and RAC2, but not CDC42. Involved in cytoskeletal rearrangements required for lymphocyte migration in response of chemokines. May also participate in IL2 transcriptional activation via the activation of RAC2.
Synonyms: KIAA0209; IMD40
Tractability: Small molecule: it has a high-quality binding pocket. Antibody: UniProt places it where antibodies can reach, with high confidence; its Gene Ontology location is reachable by antibodies, with high confidence. PROTAC: ubiquitination databases record sites on it; its protein half-life has been measured; a small molecule that binds it is known.
Gene: Protein-coding gene on chromosome 5 (169,637,249 to 170,083,382, forward strand). Ensembl gene ENSG00000134516.
Subcellular location: Endomembrane system; Cytoplasm, cytoskeleton
Pathways (Reactome):
Signal Transduction: RAC1 GTPase cycle; RAC2 GTPase cycle; RHOA GTPase cycle; RHOG GTPase cycle
Disease: Nef and signal transduction
Hemostasis: Factors involved in megakaryocyte development and platelet production
Immune System: Neutrophil degranulation
Gene Ontology:
Molecular function: guanyl-nucleotide exchange factor activity; protein binding; T cell receptor binding; small GTPase binding; GTPase activator activity
Biological process: actin cytoskeleton organization; cell migration; macropinocytosis; myeloid dendritic cell activation involved in immune response; myoblast fusion; positive regulation of phagocytosis; regulation of small GTPase mediated signal transduction; small GTPase-mediated signal transduction
Cellular component: extracellular exosome; membrane; cytoplasm; cytosol; extracellular region; plasma membrane; specific granule lumen; cytoskeleton; endomembrane system
Genetic constraint (gnomAD): Loss-of-function variants: 90 observed, 254.55 expected, observed/expected ratio (o/e) 0.35, 90% interval 0.3 to 0.42. The upper end of that interval is the gene's LOEUF score, 0.42, which puts it in group 1 of 6, group 1 being the genes least tolerant of losing a copy. Missense variants: 1,735 observed, 2,394.2 expected, observed/expected ratio (o/e) 0.72, 90% interval 0.7 to 0.75. Synonymous variants: 804 observed, 858 expected, observed/expected ratio (o/e) 0.94, 90% interval 0.88 to 0.99.
Gene-disease validity (ClinGen):
ClinGen rates the evidence that DOCK2 causes each of these diseases.
DOCK2 deficiency (autosomal recessive): Definitive.
Homologues: Orthologues: chimpanzee DOCK2 (99% identical), macaque DOCK2 (99% identical), dog DOCK2 (96% identical), pig DOCK2 (96% identical), mouse Dock2 (95% identical), guinea pig DOCK2 (95% identical), rat Dock2 (95% identical), tropical clawed frog dock2 (80% identical), Drosophila melanogaster mbc (40% identical), Caenorhabditis elegans ced-5 (26% identical). Paralogues in human: DOCK1 (60% identical), DOCK5 (55% identical), DOCK3 (37% identical), DOCK4 (36% identical), DOCK7 (17% identical), DOCK8 (17% identical), DOCK11 (17% identical), DOCK6 (16% identical), DOCK9 (16% identical), DOCK10 (16% identical).
Diseases named in the same sentence as DOCK2 in open-access papers:
DOCK2 is named in the same sentence as 90 diseases in open-access papers, as found by Europe PMC text mining. Sharing a sentence is not in itself a finding about the gene and the disease. The quoted sentences say what the papers report.
Immunodeficiency (19 papers, 2016 to 2025). Failure of the immune system to protect the body adequately from infection, due to the absence or insufficiency of some component process or substance. "Report cites the discovery of a mutation in the commercially available C57BL/6 strain, specifically gene duplication, that impairs the Dock2 gene and subsequently results in immune deficiency." (PMID 39020429, 2024). "Patients with mutations in DOCK2 present with combined immunodeficiency with early-onset invasive bacterial and viral infections." (PMID 38366567, 2024). "Homozygous DOCK2 deficiency has been implicated previously in immune dysfunction and immunodeficiencies." (PMID 36836791, 2023). "In conclusion, DOCK2 plays an important role in immunodeficiency disease and genetic testing is necessary for early diagnosis of DOCK2 deficiency or mutation." (PMID 36250020, 2022). "Positive family history of immunodeficiency and parental consanguinity were important factors in the patients that are affirmative according to the autosomal recessive inheritance of DOCK2 deficiency." (PMID 34872585, 2021). "Contrary to DOCK2 (Dedicator of Cytokinesis 2) deficiency, which has been reported to be associated with immunodeficiency diseases, variants of ELMO1 have been associated with autoimmune diseases, such as diabetes and rheumatoid arthritis (RA)." (PMID 34993193, 2021). "Another recent example are biallelic mutations of DOCK2, encoding human dedicator of cytokinesis 2, leading to combined immunodeficiencies and early-onset invasive infections." (PMID 29018476, 2017). "DOCK2 and DOCK8 physiological relevance has been underscored by the discovery of human-inherited immunodeficiencies caused by DOCK2 or DOCK8 gene mutations." (PMID 26858721, 2016). "Moreover, six unrelated patients with severe immunodeficiency caused by loss-of-function mutations in DOCK2 showed impaired responses in T cells, B cells, and NK cells." (PMID 37383235, 2023). "Indeed, a point mutation resulting in loss of DOCK2 expression was found in four siblings with severe immunodeficiency, associated with impaired actin polymerisation, polarisation and ROS production in neutrophils." (PMID 37383235, 2023). "Patients with DOCK2 mutations have been shown to be more susceptible to immunodeficiency diseases." (PMID 34621291, 2021). "DOCK2 deficiency has been reported to be associated with immunodeficiency diseases." (PMID 34993193, 2021). "As a member of the ELMO1-DOCK2 protein complex, it is known that DOCK2 deficiency can lead to inherent immunodeficiency diseases in the human population, whereas genetic polymorphism studies have shown that ELMO1 variants are associated with autoimmune diseases." (PMID 34993193, 2021). "Additionally, a recent study showed that biallelic mutations in the Dock2 gene result in severe immunodeficiency that leads to defects in actin polymerization." (PMID 28663935, 2017). "Dedicator of cytokinesis 2 (DOCK2) immunodeficiency is a disease that leads to severe immunocompromise, being fatal in 2 of the original 5 cases described, and requiring bone marrow transplantation in the other cases." (PMID 38366567, 2024). "The importance of these processes for the immune response suggests a possible disease mechanism linking DOCK2 mutations to impaired RAC1 activation and subsequent immune deficiency." (PMID 33893283, 2021). "DOCK2, an atypical guanine nucleotide exchange factor (GEF), has variants associated with immunodeficiency in T cells, B cells, and natural killer (NK) cells." (PMID 28892060, 2017). "DOCK2 deficiency should be considered in the context of severe or unusual early-onset infections, especially HHV infections, in a patient with a probable clinical diagnosis of combined immunodeficiency." (PMID 34872585, 2021). "Similarly, DOCK2 interacts with CD247, which is implicated in an immunodeficiency with similar clinical manifestations." (PMID 33893283, 2021).
Immunodeficiency (continued). "MHC Class II defect and defects in STIM1, DOCK2, SP110, ZAP70, and STK4 genes are categorized as combined immunodeficiencies as per the 2019 International Union of Immunological Societies Expert Committee classification of human inborn errors of immunity (IEI)." (PMID 33628209, 2020). "Notably, disruption of the dCS region of DOCK2 or use of dominant‐negative mutant DOCK2–dCS significantly inhibits Rac1 activation, showing potential therapeutic value for leukemia and immune diseases." (PMID 41020039, 2025). "Furthermore, the importance of Dock2 in human immune disease is not restricted to neutrophils." (PMID 37383235, 2023).
COVID-19 (14 papers, 2022 to 2026). A disease caused by infection with severe acute respiratory syndrome coronavirus 2. "Another genome-wide association study identified a variant close to the ‘dedicator of cytokinesis 2’ gene (DOCK2) from 2393 cases of COVID-19 in a cohort of Japanese individuals with 3289 unaffected controls from the Japan COVID-19 Task Force." (PMID 40362649, 2025). "A genome-wide association study (GWAS) identified that a variant on chromosome 5 at 5q35 (rs60200309-A), close to the dedicator of cytokinesis 2 gene (DOCK2), is associated with severe COVID-19 in patients less than 65 years of age." (PMID 38846354, 2024). "We recently identified a risk allele associating decreased DOCK2 expression in patients with severe COVID-19, associated with changes in monocytes, macrophages and dendritic cells." (PMID 37383235, 2023). "The first Japanese large-scale genome-wide association study (GWAS) on COVID-19 reported that genetic variants, including DOCK2, had a population-specific association with oxygenation requirements by patients with COVID-1924." (PMID 38086863, 2023). "Single-cell RNA-sequencing analysis (n = 61 individuals) identified cell-type-specific downregulation of DOCK2 and a COVID-19-specific decreasing effect of the risk allele on DOCK2 expression in non-classical monocytes." (PMID 35940203, 2022). "A genome-wide association study highlights a variant in DOCK2, which is common in East Asian populations but rare in Europeans, as a host genetic risk factor for severe COVID-19." (PMID 35940203, 2022). "We also examined the COVID-19 risk profile of the DOCK2 variant on different ancestral backgrounds (3,138 hospitalized patients with COVID-19 versus 891,375 controls from the pan-ancestry meta-analysis)." (PMID 35940203, 2022). "The A allele of the lead SNP (rs60200309), located at an intergenic region downstream of DOCK2, was associated with an increased risk of severe COVID-19 (odds ratio = 2.01, 95% confidence interval 1.58–2.55, P = 1.2 × 10−8)." (PMID 35940203, 2022). "We identified a variant on chromosome 5 at 5q35 (rs60200309-A), close to the dedicator of cytokinesis 2 gene (DOCK2), which was associated with severe COVID-19 in patients less than 65 years of age." (PMID 35940203, 2022). "We found that DOCK2 suppression is associated with the development of severe COVID-19 in a Syrian hamster model of SARS-CoV-2 infection, and that DOCK2-mediated signalling has a key role in the host immune response to SARS-CoV-2 infection." (PMID 35940203, 2022). "Finally, a variant in DOCK2 was identified in a genome-wide association study for coronavirus disease-19 (COVID-19) in Japan and found to be associated with severe outcomes in patients under 65 years old." (PMID 36836791, 2023). "Together, these results indicate that DOCK2 expression is downregulated in peripheral blood cells of patients with severe COVID-19, especially in young patients, and that the risk variant may contribute to severe COVID-19 by suppressing expression of DOCK2." (PMID 35940203, 2022). "To functionally annotate the DOCK2 risk variant, we examined the expression quantitative trait loci (eQTL) effect by conducting peripheral blood RNA-sequencing (RNA-seq) analysis of data from patients with COVID-19 collected by the JCTF (n = 473)." (PMID 35940203, 2022). "We confirmed the presence of multiple genetic variants associated with COVID-19 risk shared across different populations, identified a population-specific risk variant at DOCK2, particularly in young patients with severe COVID-19 collected during the early waves of the pandemic." (PMID 35940203, 2022). "Thus, DOCK2 expression is suppressed during severe pneumonia caused by COVID-19." (PMID 35940203, 2022). "Mutations in novel and related sHLH-associated genes, DOCK2 and DOCK8, which are important for lymphocyte cytolytic activity, have also been linked to severe COVID-19 and post-COVID-19 multi-system inflammatory syndrome in children (MIS-C), respectively." (PMID 40872807, 2025).
COVID-19 (continued). "COBL, GPX3 and SOCS3 were lower in the early and late secretory phase in women with COVID-19, whereas DOCK2 and SLC2A3 were unchanged." (PMID 38372528, 2024). "A risk allele associated with decreased DOCK2 expression is seen in patients with severe COVID-19, and inhibition of DOCK2 with the small molecule inhibitor CPYPP increased pneumonia severity in a hamster model of SARS-CoV-2 infection." (PMID 38077328, 2023). "We observed a loss of DOCK2 expression in lymphocytes in a case of non-COVID-19 severe pneumonia, whereas there was a slight decrease of DOCK2 expression in a sample from a case of non-COVID-19 mild pneumonia." (PMID 35940203, 2022). "Elucidation of immune cell-type-specific expression profiles was necessary to disentangle the roles of DOCK2 in the biology of COVID-19." (PMID 35940203, 2022). "Assays with increased DOCK2 expression would provide further evidence of its role in COVID-19 pathophysiology." (PMID 35940203, 2022). "To confirm the involvement of DOCK2 in COVID-19 pneumonia, we performed immunohistochemical analysis on postmortem samples from people who died from COVID-19." (PMID 35940203, 2022). "Our results motivate further studies linking DOCK2 to molecular and clinical phenotypes of COVID-19 in the effort to overcome the pandemic." (PMID 35940203, 2022). "To decipher in vivo pathogenesis of DOCK2 in COVID-19, we investigated the effects of DOCK2 suppression following SARS-CoV-2 infection in a Syrian hamster model." (PMID 35940203, 2022). "Furthermore, GWAS can miss yet-to-be-identified novel variants (e.g. in Asians) not incorporated into existing genotyping arrays, as exemplified by the recent identification of DOCK2 (dedicator of cytokinesis 2) in the Japanese COVID-19 cohort." (PMID 40534864, 2025). "Significant inhibition of DOCK2 expression has been found in COVID-19 patients." (PMID 36250020, 2022). "Population-specific features of the DOCK2 variant provide a rationale for COVID-19 host genetic research in non-European populations." (PMID 35940203, 2022). "We found a COVID-19 context-specific decreasing dosage effect of the risk variant on DOCK2 expression in non-classical monocytes (β = −0.21, P = 0.035 for COVID-19 and β = 0.02, P = 0.51 for controls)." (PMID 35940203, 2022). "DOCK2 expression was reduced in the patients with severe COVID-19 (P = 0.011)." (PMID 35940203, 2022). "DOCK2 expression was suppressed in patients with severe cases of COVID-19." (PMID 35940203, 2022). "Furthermore, single-cell RNA sequencing revealed cell type-specific suppression of DOCK2, with the risk allele exerting a COVID-19-specific inhibitory effect on DOCK2 expression in non-classical monocytes." (PMID 40362649, 2025). "This in silico model predicted that five genes important for embryo implantation were affected by COVID-19 (down-regulation of COBL, GPX3 and SOCS3, and up-regulation of DOCK2 and SLC2A3)." (PMID 38372528, 2024). "We analysed differential expression of DOCK2 in patients with severe and non-severe COVID-19 (n = 468) using real-time quantitative PCR (qPCR)." (PMID 35940203, 2022). "In recent studies, researchers have found that DOCK2 plays an important role in the host immune response to severe acute respiratory syndrome coronavirus 2 (SARS-CoV-2) infection and the development of coronavirus disease 2019(COVID-19)." (PMID 36250020, 2022). "We conclude that DOCK2 has an important role in the host immune response to SARS-CoV-2 infection and the development of severe COVID-19, and could be further explored as a potential biomarker and/or therapeutic target." (PMID 35940203, 2022). "It is not clear that DOCK2 has a different mechanism between ALI and COVID-19." (PMID 36250020, 2022).
colorectal cancer (11 papers, 2016 to 2024). A primary or metastatic malignant neoplasm that affects the colon or rectum. "DOCK2 has been identified to be associated with prognostic factors in a variety of cancer types, such as acute myeloid leukemia, prostate cancer, colorectal cancer, and non-small cell lung cancer, indicating that DOCK2 is a promising therapeutic target." (PMID 36250020, 2022). "Studies have shown that genetic mutations in IKZF1 are associated with poor prognosis in hematologic tumors and colorectal tumors; Low expression of DOCK2 is associated with a poor prognosis in colorectal cancer and lung cancer patients." (PMID 36311703, 2022). "Another study also showed that DOCK2 was significantly associated with survival outcome in colorectal cancer." (PMID 32850314, 2020). "Low expression of DOCK2 is associated with poorer prognosis in colorectal cancer." (PMID 31762818, 2019). "Here, we investigated the function of Dock2, a gene mutated in ~10% of IBD-associated colorectal cancers that encodes a guanine nucleotide exchange factor (GEF)." (PMID 39242821, 2024). "By studying human samples and clinical data from 481 colorectal cancer patients, the researchers found that DOCK2 expression levels were positively correlated with overall survival." (PMID 36250020, 2022). "Investigation of DOCK2 and PTPRC somatic mutations in colorectal cancer revealed a fairly high frequency (10% and 8%, respectively) of genetic alterations in tumors." (PMID 33968341, 2021). "Although it is predominantly expressed in lymphocytes and hematopoietic tissues, recent research has revealed the tumor-promoting role of DOCK2 in lymphoma and colorectal cancer." (PMID 34783629, 2021). "On the other hand, DOCK2 acted as an important participant in 4-gene signature for hypermutated colorectal cancer to identify suitable patients for immunotherapy." (PMID 34621291, 2021). "In general, the expression level of DOCK2 may serve as a new prognostic indicator to help evaluate patients with colorectal cancer and predict different clinical outcomes." (PMID 36250020, 2022). "In addition, lower DOCK2 expression was related to a poorer prognosis in colorectal cancer, which was attributed to the regulation of canonical and noncanonical Wnt signaling." (PMID 35620462, 2022).
prostate carcinoma (9 papers, 2010 to 2022). A carcinoma that arises from epithelial cells of the prostate gland. "In summary, DOCK2 has great potential to become a diagnostic and prognostic biomarker for PCa, but its specific mechanisms and signaling pathways in prostate cancer need also to be further explored." (PMID 36250020, 2022). "Recent study reported that DOCK2 hypermethylation was associated with biochemical recurrence after radical prostatectomy in prostate cancer." (PMID 32867782, 2020). "However, the expression level of DOCK2 is positively correlated with the proliferation rate of CXCL13-induced prostate cancer cells." (PMID 31762818, 2019). "In prostate cancer, many specifically hypermethylated genes were found, including DOCK2, GRASP, HIF3A, and PKFP, among which DOCK2 is the candidate marker with the greatest potentiality." (PMID 35620462, 2022). "Signaling studies revealed that DOCK2 (Dedicator of cytokinesis 2), ERK1/2, JNK and Akt signals mediate CXCL13 invasive and proliferative responses in prostate cancer cells." (PMID 31354634, 2019). "Plasma from 36 healthy subjects, 61 patients with benign prostatic hyperplasia (BPH), 102 patients with limited prostate cancer and 65 patients with early metastatic PCa (MPCA) were examined, and hypermethylated DOCK2 was detected in the plasma of MPCA patients." (PMID 36250020, 2022). "DOCK2 as a guanine nucleotide exchange factor (GEF) belongs to the dedicators of cytokinesis (DOCK) family, which originally identified in hematopoietic cell, and now it is also studied in B‐cell lymphoma and prostate cancer." (PMID 33259129, 2021).